PPARG (peroxisome proliferator activated receptor gamma)
Diseases named in the same sentence as PPARG in open-access papers (continued):
Sharing a sentence is not in itself a finding about the gene and the disease.
Sepsis (101 papers, 2007 to 2026). Sepsis is defined as life-threatening organ dysfunction caused by a dysregulated host response to infection. "ROC curve analysis was performed to evaluate the diagnostic value of ABCC1, CYP1B1, and PPARG in sepsis patients." (PMID 41509654, 2026). "Although considerable research has verified the association between PPARγ and pyroptosis in other conditions, including ulcerative colitis, sepsis and osteoarthritis, only a few studies have investigated this relationship in the context of GA." (PMID 38773379, 2024). "The pleiotropic effects of PPARγ agonists make them great candidates for therapy associated with antibiotics in sepsis." (PMID 35563317, 2022). "Genetic variations in the PPARG gene were linked to the outcome of sepsis and PPARG was suggested as a novel biomarker for sepsis." (PMID 34573990, 2021). "Sepsis causes changes in PPARγ expression and activation, in part because of phosphorylation of PPARγ by ERK1/2." (PMID 33467433, 2021). "There was a significant association between the rs10865710 polymorphism in the PPARγ gene and the risk of sepsis and MODS in trauma patients." (PMID 27023591, 2016). "Our results showed that the rs10865710 in the PPARγ gene revealed a strong clinical relevance with a higher rate of sepsis and MOD scores in the trauma patients with the variant G allele." (PMID 27023591, 2016). "As rs10865710C/G may play a role in traumatic sepsis susceptibility and transcriptional regulation of PPARG mRNA, we next focused on determining which transacting factor binds to rs10865710C/G." (PMID 31888703, 2019). "Numerous in vivo and in vitro studies have shown that administration of PPARγ agonists can suppress the inflammatory responses associated with sepsis, acute lung injury, and inflammation, increasing the host’s ability to kill and clear pathogenic bacteria and improving prognosis." (PMID 31888703, 2019). "Our study provides evidence that the enhancer-region polymorphism rs10865710 might influence transcription factor binding and regulate PPARγ expression, thus conferring susceptibility to traumatic sepsis." (PMID 31888703, 2019). "Patients carrying a mutated PPARG gene might be susceptible to excessive inflammatory responses, sepsis, and/or poor prognosis." (PMID 31888703, 2019). "Our two-stage cohort genetic association study integrating biological experiments provided solid evidence that rs10865710 may decrease transcriptional activity and PPARG expression, thus conferring susceptibility to traumatic sepsis." (PMID 31888703, 2019). "Given the central role of PPARG in the pathogenesis of traumatic sepsis, we hypothesize that rs10865710 polymorphism may impact PPARG expression and the occurrence of sepsis in trauma patients." (PMID 31888703, 2019). "Thus, the correlation between Grail and PPARγ during the modulation of sepsis development and the possible associated molecular mechanisms is worth further study." (PMID 30571701, 2018). "In our study, the rs10865710 polymorphism in the PPARγ gene could affect TNFα production and was associated with the development of sepsis and MODS in Chinese Han trauma patients." (PMID 27023591, 2016). "Therefore, integrating the results of e-QTL analysis and the important role that rs10865710 plays in regulating expression of PPARG, we propose that rs10865710 contributes to traumatic sepsis susceptibility by impacting transcription and further affecting expression of PPARG." (PMID 31888703, 2019). "Consequently, a pivotal involvement of PPARγ in T cell apoptosis was hypothesized what might contribute to lymphocyte loss and breakdown of defense mechanisms during sepsis." (PMID 22481914, 2012). "Using machine learning algorithms, we identified three key diagnostic genes for sepsis (ABCC1, CYP1B1, and PPARG) with high reliability and broad applicability." (PMID 41509654, 2026).
Sepsis (continued). "The results demonstrated that ABCC1 was significantly downregulated, while CYP1B1 and PPARG were significantly upregulated in the sepsis organoids." (PMID 41509654, 2026). "Single-cell analysis further revealed that ABCC1, CYP1B1, and PPARG are highly expressed in monocytes, which are central to the immunopathology of sepsis, acting as key mediators of both inflammation and immune suppression." (PMID 41509654, 2026). "Research has found that PPARG can reduce pyroptosis and liver damage during sepsis by inhibiting ROS levels and suppressing the TXNIP/NLRP3 signaling pathway." (PMID 40070882, 2025). "Studies show that mTOR can exacerbate pyroptosis of CD4+ T cells by negatively regulating the PPARγ-Nrf2 signaling pathway, promoting the occurrence of sepsis-related immune suppression and ultimately resulting in poor clinical prognosis." (PMID 41244772, 2025). "Some findings are consistent with our study, for instance, IL17A, IL1B, MBL, NOD2, PPARG and SOD2 genes were associated with sepsis." (PMID 40168842, 2025). "Nrf2 has been shown to play a protective role in sepsis-induced pulmonary injury and inflammation by modulating autophagy and NF-κB/PPARγ-mediated macrophage polarization." (PMID 39915460, 2025). "OA‐rich EN can be rapidly absorbed by the intestinal tract and activate PPARγ in the intestine, thereby alleviating sepsis‐induced acute intestinal injury." (PMID 41256230, 2025). "Sepsis models have revealed a critical role for PPARγ in controlling inflammation and improving overall disease outcomes." (PMID 40717128, 2025). "Previous studies on sepsis have shown that OA‐rich EN can be rapidly absorbed by the intestinal tract and activate PPARγ in the intestine and liver, thereby alleviating acute intestinal and liver injury." (PMID 41256230, 2025). "Among the myriad genes, IER3, DSC2, and PPARG emerged as linchpins, their prominence in sepsis further validated through ROC analytics." (PMID 39331858, 2024). "Harnessing the expression profiles of pivotal glycolytic genes: PPARG, DSC2, and IER3: we’ve devised a predictive model that seeks to revolutionize the diagnostic approach to sepsis." (PMID 39331858, 2024). "Many studies have shown abnormal expression of PPARα and PPARγ in the pathological state of sepsis, which is closely related to patient prognosis." (PMID 39019343, 2024). "Mechanistic investigations revealed that PGZ activated the PPARγ/PGC-1α/mitochondrial protection pathway to prevent sepsis-induced ALI by inhibiting M1 macrophage polarization." (PMID 38511769, 2024). "The detailed mechanism is unclear; however, PPARγ-induced cardiolipotoxicity is ameliorated by deleting PPARα, and PPARγ activation seems to be protective in sepsis-related cardiac dysfunction." (PMID 37233656, 2023). "Once again, although there are already studies on PPARγ activation in sepsis, including our own articles, little is known about PPARγ in microglia during infection, especially when trying to mitigate SAE." (PMID 35563317, 2022). "In sepsis, PPARγ has a pivotal role, with in vitro and in vivo showing beneficial effects in the inflammatory response control upon its activation." (PMID 35563317, 2022). "Increased expression of PPARγ also decreased sepsis-induced reactive oxygen species (ROS) by promoting the expression of Nrf2." (PMID 35136484, 2022). "In conclusion, our clinical studies, as well as the in vivo and in vitro experiments, show that Nrf2 plays a protective role in sepsis-induced lung injury and inflammation by the regulation of autophagy-and NF-κB/PPARγ-mediated macrophage polarization." (PMID 36497185, 2022). "In conclusion, these results indicate that Nrf2 plays a protective role in sepsis-induced pulmonary injury and inflammation through the regulation of autophagy- and NF-κB/PPARγ-mediated macrophage polarization." (PMID 36497185, 2022). "Based on these results, we conclude that PPARγ has a protective effect on liver function during sepsis." (PMID 35136484, 2022).
Sepsis (continued). "The administration of a PPARγ antagonist to burned mice abolished the protective effect of pioglitazone against sepsis after bacterial infection." (PMID 36361535, 2022). "Curcumin’s therapeutic effect in sepsis appears to be achieved by activation of peroxisome proliferator-activated receptor gamma (PPAR-γ), which leads to inhibition of pro-inflammatory cytokine along with expression and release of TNF-α." (PMID 35401176, 2022). "Based on these results, we conclude that PPARγ and Nrf2 activation can alleviate inflammatory responses and pyroptosis in mouse livers during sepsis." (PMID 35136484, 2022). "Evidence shows that PPARγ activation decreases inflammatory and apoptotic levels, prolonging the survival rate in sepsis-induced acute lung injury." (PMID 35563317, 2022). "Our findings showed that PPARγ activation by pioglitazone improved the outcomes of severely burn-injured mice after E. coli challenge and sepsis." (PMID 36361535, 2022). "Our review suggests PPARγ as a molecular target for studies involving the effects of sepsis in the SNC, based on its anti-oxidant, anti-inflammatory and pro-resolutive properties, which are already well established in the literature for many diseases." (PMID 35563317, 2022). "PPARγ activation also attenuates liver dysfunction, one of the most vulnerable organs in sepsis, having a significant impact on the progression of the disease since liver metabolic functions are vital players in sepsis development." (PMID 35563317, 2022). "This protective effect in sepsis is partially due to the PPARγ effects on macrophages, increasing their phagocytic capability, improving pathogen clearance, and mediating M2 polarization and resolution of inflammation." (PMID 35563317, 2022). "Naringin also improved sepsis-induced intestinal injury by modulating macrophage polarization via PPARγ/miR-21 axis." (PMID 36588685, 2022). "In this study, we observed that PPARγ strongly reduced ROS-mediated injury in hepatocytes during sepsis both in vivo and in vitro." (PMID 35136484, 2022). "To conclude, GPR43 is involved in the inactivation of NLRP3 inflammasome in sepsis model by ROS-induced mitochondrial damage via PPARγ/ EBP50/Nox1/p47phox." (PMID 34584017, 2021). "In relation to inflammatory conditions such as sepsis, PPARγ agonists effectively suppress pro-inflammatory cytokine production and appear to be beneficial in alleviating organ injury and dysfunction, which has promising potential for therapeutic development." (PMID 34575939, 2021). "In relation to myocardial dysfunction, a separate study in rats assessed the mechanism of PPARγ-mediated cardiac protective effects in sepsis." (PMID 34575939, 2021). "While few studies have assessed the impact of PPARγ agonists on skeletal muscle inflammation and metabolism during inflammatory disorders such as sepsis, there has been some work surrounding the protective effects of PPARγ on myocardial dysfunction in sepsis." (PMID 34575939, 2021). "Accumulating evidence in animal studies demonstrated that PPARγ agonists improved the outcomes of sepsis via multiple mechanisms." (PMID 34394992, 2021). "It is proposed to have a protection effect during the sepsis course by acting as the peroxisome proliferator-activated receptor-gamma (PPARγ) agonist." (PMID 34394992, 2021). "Together with previous findings, our results indicate that GRP43 alleviated mitochondrial damage in macrophage by the promotion of ROS production to alleviate NLRP3 inflammasome of sepsis model by PPARγ/ Nox1/ EBP50/p47phox signaling." (PMID 34584017, 2021). "In this study, EBP50/Nox1/p47phox is involved in the activation of NLRP3 Inflammasome in sepsis model by the inhibition of GPR43 via PPARγ." (PMID 34584017, 2021). "To further understand the mechanism of GE in sepsis-induced kidney injury, we measured the effect of GE on PPARγ signaling using western blot and immune histochemical analysis." (PMID 33197894, 2020).
Sepsis (continued). "PPARγ also protected the brain against microvascular dysfunction in sepsis, including diminished leukocyte/endothelial cell interaction and increased functional capillary density in the brain, improving cerebral perfusion." (PMID 32599864, 2020). "The activation of PPARγ reduces sepsis-induced lung injury and inflammatory cell infiltration into intestinal tissues, and also prevents sepsis-induced myocardial dysfunction through reducing pro-inflammatory cytokines, apoptosis and necroptosis." (PMID 33197894, 2020). "The beneficial anti-inflammatory role of omega-9 in sepsis possibly can occur through a mechanism dependent on PPARγ expression and can join the many described beneficial properties of NEFA-enriched diets in inflammatory diseases." (PMID 32599864, 2020). "Sepsis models have revealed a critical role for PPARγ in controlling inflammation and improving the overall disease outcome." (PMID 30897154, 2019). "Treatment with PPARγ agonists improved sepsis outcome, decreasing pro-inflammatory cytokines, increasing IL-10 levels, and improving mouse survival." (PMID 30897154, 2019). "For example, the level of PPARγ expression was found to be reduced in freshly isolated mononuclear cells from sepsis patients as well as in the lungs in sepsis murine models." (PMID 31888703, 2019). "Accordingly, PPARγ and its ligands have become novel therapeutic targets for the treatment of sepsis and other inflammatory diseases." (PMID 31888703, 2019). "PPARγ gene expression was down-regulated in freshly isolated peripheral blood mononuclear cells (PBMCs) from human sepsis patients as well as in the lungs in a murine sepsis model." (PMID 30897154, 2019). "The enzyme PRMT1 was also recently shown to regulate PPARγ’s activity in macrophages in the cecal ligation and puncture sepsis models." (PMID 30897154, 2019). "In a recent study, a PPARγ response element was identified in the microRNA-124 (miR-124) promoter region, and expression of miR-124 was decreased in human sepsis patients and was critical for preventing an exaggerated inflammatory response in septic mice." (PMID 30897154, 2019). "Orally administered probiotics have also been shown to protect against sepsis-induced liver and colonic damage in mice through the activation of PPARγ." (PMID 30524427, 2018). "Peroxisome proliferator-activated receptor γ (PPARγ) is considered a promising target for sepsis treatment." (PMID 30571701, 2018). "The protective effect of PPARγ activation is also demonstrated in mouse and rat models of polymicrobial sepsis using cecal ligation and puncture (CLP)." (PMID 27774097, 2016). "In the context of sepsis-associated pulmonary injury, miRNAs interfere with JNK/PPARγ and cholinergic pathways which, in turn, contribute to pulmonary inflammation or inflammatory resolution." (PMID 27890015, 2016). "The authors therefore concluded that PPARγ activation contributes to the lymphopenia observed during sepsis." (PMID 27774097, 2016). "These two ligands were able to rescue sepsis-induced decreases in PPARγ expression in the lung to normal constitutive levels." (PMID 26713087, 2015). "Recently, peroxisome proliferator-activated receptor gamma (PPAR-γ) was described as playing a role in modulating the pathological status of sepsis by regulating energy metabolism, inflammation, and immune cell function." (PMID 25152754, 2014). "When sepsis was induced in mice, chemotaxis of neutrophils was suppressed compared to healthy mice, but treatment with a PPARγ antagonist restored chemotactic activity to control levels." (PMID 22481914, 2012). "In an animal model of sepsis, sepsis-induced T cell depletion was abrogated after application of a PPARγ antagonist." (PMID 22481914, 2012). "Neutrophils represent the central cellular component in the sepsis-induced innate immune response and were previously shown to express PPARγ." (PMID 22481914, 2012).
Sepsis (continued). "In a rodent model of polymicrobial sepsis, both PPARγ and PPARβ/δ activation limited the extent of organ dysfunction caused by cecal ligation and puncture (CLP)." (PMID 22481914, 2012). "However, PPARγ agonism was also found to contribute to function loss of neutrophils and depletion of lymphocytes what might be deleterious in the immunosuppressive phase of sepsis." (PMID 22481914, 2012). "Additionally, the predominant expression of ABCC1, CYP1B1, and PPARG in monocytes underscores the critical role of monocyte functional reprogramming in sepsis pathogenesis." (PMID 41509654, 2026). "Additionally, three key genes (ABCC1, CYP1B1, and PPARG) were identified based on Prevotella 9, fatty acids, and PANoptosis, contributing to sepsis progression via the regulation of neutrophils, oxidative stress, and macrophage polarization." (PMID 41509654, 2026). "Similarly, the dual regulatory effects of PPARG on metabolic pathways and immune cells underscore its role in metabolic adaptation during sepsis-induced immune suppression." (PMID 41509654, 2026). "Through bioinformatics analysis, we identified five genes associated with ferroptosis—MAPK3, MAPK8, PPARG, PTEN, and STAT3—that may contribute to sepsis-related tissue damage." (PMID 40070882, 2025). "This suggested that PGZ treatment in sepsis establishes a PPARγ/PGC-1α positive feedback loop, which could further potentiate its effects of activating mitochondrial function and exerting anti-inflammatory actions." (PMID 38511769, 2024). "However, utilization of FFAs through β-oxidation is impaired in the early course of sepsis, possibly by the downregulation of PPARγ signaling, a key regulator in gene expression for mitochondrial lipid utilization." (PMID 36982590, 2023). "PPARγ has also been confirmed to play an essential regulatory role in inflammation and sepsis." (PMID 37206244, 2023). "This may be strengthened by recent findings showing an upregulation of peroxisome proliferator-activated receptor gamma (PPARγ) signaling in sepsis, through which PGC1α could express its anti-inflammatory function." (PMID 36982590, 2023). "Furthermore, we showed that omega-9 improved bacterial clearance, possibly involving PPARγ, which contributed to a better sepsis outcome." (PMID 35563317, 2022). "In addition, upregulated PPARγ inhibited the expression of the TXNIP/NLRP3 signaling pathway by reducing ROS-induced injury in the liver during sepsis, which further reduced NLRP3-mediated pyroptosis and the inflammatory response." (PMID 35136484, 2022). "Also, the anti-inflammatory effect of curcumin in an experimental model of sepsis was found to be mediated by upregulation of peroxisome proliferator-activated receptor-γ (PPARγ)." (PMID 36588685, 2022). "Notably, the PPARγ agonists and the co-activator PGC-1ß have been implicated in the reduction of muscle protein catabolism during sepsis in animal models." (PMID 36335235, 2022). "Activation of PPARγ suppressed the inflammatory responses in the liver during sepsis." (PMID 35136484, 2022). "Additionally, PPARγ diminishes sepsis-induced acute kidney injury, one of the most common complications observed during sepsis, in up to 70% of all patients." (PMID 35563317, 2022). "Notably, this study showed that GPR43 induced PAK4 and PPARγ protein expressions and suppressed Nox1 protein expression in macrophage by LPS+ATP or mice model of sepsis." (PMID 34584017, 2021). "Thus, the effects of PPARγ agonism on muscle inflammation and protein and carbohydrate metabolism will be highlighted, particularly with its potential relevance in sepsis-related metabolic dysfunction." (PMID 34575939, 2021). "Next, we explored whether PPARγ was functionally involved in GPR43’s induction of NLRP3 Inflammasome in sepsis model." (PMID 34584017, 2021). "During sepsis, omega 9 restores PPARγ expression and controls exacerbated inflammation." (PMID 33467433, 2021).